CTLA4 (cytotoxic T-lymphocyte associated protein 4)
Diseases named in the same sentence as CTLA4 in open-access papers (continued):
Sharing a sentence is not in itself a finding about the gene and the disease.
tumor (continued). "225Ac-anti-CCR8 RIT alone demonstrated effectiveness in CRC models but dramatic anti-tumor response was observed when it was combined with anti-CTLA-4 immunotherapy." (PMID 41035646, 2025). "CTLA-4 inhibition enhances T cell activation and IFN-γ secretion, which in turn upregulates PD-L1 expression on tumor cells, undermining CTLA-4 monotherapy efficacy." (PMID 40666508, 2025). "Recently, anti-CTLA4 therapy has been used successfully to re-invigorate T cell-mediated anti-tumour immune responses by blocking CTLA4-mediated suppression of CD28 function." (PMID 40496752, 2025). "(ICIs), such as anti-PD-1 and anti-CTLA-4, reawaken T cells that have been inhibited by the tumor microenvironment, thereby reinstating anti-tumor immunity and possibly averting latent tumor cells from evading immune surveillance and triggering metastasis." (PMID 41465319, 2025). "Blocking CTLA-4 in the tumor microenvironment potentiates T-cell activation, leading to stronger anti-tumor responses driven by CD8+ T cells." (PMID 40535343, 2025). "Several inhibitory markers, including CD276, HAVCR2, CTLA4, PDCD1LG2, LAIR1, and ADORA2A, were significantly upregulated in the high-risk group (p < 0.05), suggesting an immunosuppressive tumor microenvironment." (PMID 40963600, 2025). "When combined with anti-CTLA-4 checkpoint blockade, the therapy produced synergistic tumor regression, demonstrating how VSV’s innate immune activation can be leveraged to boost the efficacy of ICIs." (PMID 41294689, 2025). "The tumor immune checkpoint, such as PD-L1 and CTLA-4, are currently the most extensively and well-researched clinical studies." (PMID 40178680, 2025). "Anti-CTLA-4 immunotherapy mainly enhances anti-tumor immune response through the elimination of Tregs." (PMID 40296912, 2025). "CTLA-4 plays a crucial role in modulating immune responses in TNBC by influencing tumor immune evasion mechanisms." (PMID 40281554, 2025). "Our data suggest an important contribution of Tbet+ICOS+ Th1-like CD4+ T cells in the remodeling of tumor blood vessels and the increase of TA-HEVs during treatment with anti-CTLA-4 antibodies." (PMID 40460830, 2025). "Blocking CTLA4, PD-1, and PD-L1 inhibitory effects can promote and enable effective immune responses against tumor cells." (PMID 40777043, 2025). "In parallel, bispecific antibodies have been engineered to co-target PD-1 and CTLA-4 in a structurally optimized and tumor-selective manner." (PMID 41013723, 2025). "This environment results in the aberrant expression of checkpoint-related genes, such as CTLA-4, PD-1, and PD-L1, which can promote immune evasion and tumor progression." (PMID 39151098, 2025). "As expected, anti-CTLA4 monotherapy induced significant tumor regression in subcutaneous models, whereas orthotopic tumors exhibited primary resistance to CTLA4 blockade." (PMID 40899264, 2025). "In the present study, we found a significant correlation between CTLA-4 intensity scores and the percentage of tumor distribution within paraffin-embedded HNSCC tissue samples." (PMID 40861696, 2025). "Combined with anti–CTLA–4 therapy, this strategy significantly improved anti-tumor immunity and survival." (PMID 40507337, 2025). "Meanwhile, results from syngeneic mouse models indicated that PLA2G7 suppression and anti-CTLA4 therapy have synergistic effects on tumor burden and mouse survival." (PMID 40169540, 2025). "We found that anti-CTLA-4 antibodies remodel tumor vasculature and increase TA-HEVs through Fc-dependent mechanisms." (PMID 40460830, 2025). "Blood‐circulating CD8 T cells showed IFN‐γ and granzyme B (GrB) hyperfunction in response to anti‐CD3/28 stimulation, as well as impaired responses to ectopic tumour challenge and anti‐PD‐1/CTLA‐4 immunotherapy." (PMID 40760842, 2025). "Whereas blockage of the PD1/PDL1 system prevents inhibition of T cell function, blockage of CTLA4 induces expansion of tumor reactive T cells." (PMID 40124507, 2025).
tumor (continued). "Starting from the success of anti-CTLA-4 antibody therapy in malignant melanoma, targeted immunotherapy has emerged as one of the most effective strategies for anti-tumor therapy, igniting a new wave of research in tumor immunotherapy." (PMID 40722845, 2025). "Tregs can upregulate immune checkpoint molecules, such as CTLA-4 and PD-1, which can dampen the activity of anti-tumor immune cells and limit the efficacy of ICB therapy." (PMID 40959055, 2025). "We found minimal expression of PD1, LAG3, and CTLA4 on both CB- and AD-8F4CAR-iNK T cells suggesting unimpaired anti-tumor function." (PMID 40519924, 2025). "Combining MRTX1133 with immune checkpoint blockades such as anti-PD-1 or anti-CTLA-4 antibodies led to enhanced antitumor immunity, tumor eradication, and prolonged OS in preclinical models." (PMID 40805153, 2025). "Tumor antigens that have been successfully targeted include epidermal growth factor receptor (EGFR), ERBB2, vascular endothelial growth factor (VEGF), cytotoxic T lymphocyte-associated antigen 4 (CTLA4), CD20, CD30 and CD52." (PMID 41294857, 2025). "ICIs act inhibiting tumor immune escape by targeting PD-1 and its ligand (PD-L1), lymphocyte-activating gene-3 (LAG3), cytotoxic T lymphocyte-associated antigen-4 (CTLA-4), and other targets." (PMID 40944286, 2025). "CTLA-4 IHC staining in tumors localizes its expression on TILs (tumor-infiltrating lymphocytes) and, less frequently, on tumor cells." (PMID 40941632, 2025). "GMDP signals through NOD2 on myeloid cells to release IL-1b and NLRP3 to induce cytotoxic granzyme B+CD8+ T cells in the tumor and enhances the efficacy of anti–CTLA-4, anti–PD-1, and anti–PD-L1 in different mouse tumor models." (PMID 39895632, 2025). "Its mechanism of action is to enhance the metabolic response of T cells by inhibiting CTLA-4, thus helping the immune system to recognize and attack tumor cells." (PMID 40696413, 2025). "However, immunosuppressive tumor-associated macrophages (TAMs) remained prevalent and expressed ligands for alternative checkpoints such as CTLA-4 and TIGIT, suggesting that targeting these pathways may be necessary to overcome TAM-mediated suppression and improve anti-tumor immunity." (PMID 40960500, 2025). "It is further reported that CD73 blockade, which has also been shown to increase the efficacy of both anti-CTLA-4 and anti-PD-L1 therapies, enhances the efficacy of radiotherapy by promoting the anti-tumor activity of the immune system." (PMID 41235226, 2025). "By targeting the PD-1/PD-L1 and CTLA-4 pathways, ICIs help restore antitumor immunity and promote more effective immune-mediated tumor elimination." (PMID 41013723, 2025). "In the context of cancer immunotherapy, blocking CTLA-4 enhances the proliferation and activation of T lymphocytes targeting tumor cells." (PMID 41357215, 2025). "CTLA-4 is highly expressed on Tregs, especially within the tumor microenvironment, making them a key target of CTLA-4 blockade." (PMID 40558520, 2025). "A study has shown that in HCC, activated Tregs within the tumor exhibit high expression levels of various inhibitory molecules, including CTLA-4 and TNFRSF9." (PMID 41514551, 2025). "By analyzing immune evasion mechanisms within the tumor microenvironment, it helps predict patient responses to immune checkpoint inhibitors, such as PD-1 or CTLA-4 inhibitors." (PMID 40843931, 2025). "By contrast, anti-CTLA-4 antibody treatment resulted in complete tumor regression in both CT26-mock and CT26-ULBP2 models." (PMID 40558520, 2025). "Studies have shown that combining ICIs like tremelimumab (anti-CTLA-4) with local ablation enhances CD8+ T cell activity in the tumor periphery, resulting in promising antitumor effects." (PMID 40843361, 2025). "Studies have suggested that compared to Tregs in peripheral blood, tumor-infiltrating Tregs exhibit more proliferative and immunosuppressive phenotypes, with increased expression of CTLA-4, CD25, GITR, 4−1BB, OX40, ICOS, LAG-3, TIM3, TIGIT, and PD-1." (PMID 40587482, 2025).
tumor (continued). "HCC tumours exhibit immune suppression through multiple mechanisms, including the upregulation of immune checkpoint molecules such as PD-1, CTLA-4 and TIM-3, which contribute to T-cell exhaustion." (PMID 41561544, 2025). "The STRIDE regimen, involving dual blockade of PD-L1 and CTLA-4, significantly enhanced antitumor immunity, as evidenced by extensive tumor necrosis and lymphoplasmacytic infiltration." (PMID 40500480, 2025). "We also clearly identified that high proportions of LAG3+, TIM3+, and CTLA4+ tumor-infiltrating iNKT cells were predictive of poor clinical outcomes." (PMID 41562072, 2025). "In contrast, the addition of CTLA-4 blockade enhanced antitumor activity, with combination therapy inducing objective tumor regression and more durable disease stabilization, in line with results from larger retrospective and phase II studies." (PMID 41228313, 2025). "TOX is a positive regulator of PD-1, TIM3, TIGIT, and CTLA-4 expression in tumor-infiltrating CD8+ T cells." (PMID 40075727, 2025). "Inhibition of SLC13A3 in syngeneic mouse tumor models synergizes with CTLA-4 blockade therapy to promote tumor-infiltrating T-cell immune responses, providing a potential novel therapeutic strategy for multiple cancer types." (PMID 41226585, 2025). "Tumors can selectively inhibit T-cell function through both contact-dependent and independent mechanisms, as well as T-cell exhaustion, by upregulating PD-L1 expression on tumor cells and PD-1 and CTLA-4 expression on T cells." (PMID 40831543, 2025). "Low risk score indicated had a lower tumor escape score, lower TIDE score, higher TMB score and higher CTLA4&PD1 immunophenoscore, suggesting a better immunotherapy response." (PMID 40612112, 2025). "ICscore has shown promise in stratifying responders to ICIs like anti-PD-L1 and anti-CTLA-4 therapies and correlates negatively with markers of tumor immune escape." (PMID 40177538, 2025). "This unique tumor cluster exhibited high gene expression of 22 genes, including immune checkpoint regulators, like CTLA4, TIGIT, LAG3, and CD27, immune cell surface markers, and inflammatory genes." (PMID 40492347, 2025). "In the time post-treatment but pre-surgery, reduction in the median value of cfDNA, higher levels of M-MDSC, lower levels of CTLA4+ Treg or PD1+ Treg and SIS changes on MRI were associated with an increased tumor response." (PMID 40647527, 2025). "By blocking PD-1 or CTLA-4, ICIs remove inhibitory checkpoints on T-cells, which can then attack normal tissues expressing antigens that the immune system finds similar to tumor antigens or that were previously tolerated." (PMID 41568391, 2025). "In the current study, we aimed to evaluate potential synergy of our agent with anti–CTLA-4 antibody therapy in MC38 tumor–bearing mice to provide proof-of-concept for additional potential clinical studies in patients." (PMID 39881590, 2025). "Tumor cells themselves exploit immune checkpoint pathways, such as PD-1/PD-L1 and CTLA-4 signaling, to evade immune recognition, making it difficult for T cells to mount an effective response." (PMID 40660400, 2025). "Simultaneous inhibition of CTLA-4 and PD-1/PD-L1 pathways results in complementary anti-tumor phenomena, and anti-PD-1 combined with anti-CTLA-4 immunosuppressants clearly prolongs the overall survival of patients with advanced NSCLC." (PMID 40296912, 2025). "A specific domain within CTLA‐4 conveys inhibitory signals to T cells, thereby diminishing the immune response, which facilitates the proliferation and dissemination of tumor cells." (PMID 40551477, 2025). "By blocking the binding of CTLA-4 and CD80, anti-CTLA-4 antibodies can reactivate the function of tumor-infiltrating T cells." (PMID 39941829, 2025). "Combining Gvax with CTLA-4 blockade resulted in increased infiltration of effector T cells into the tumor and a significant shift in the balance between Tregs and effector T cells (Teffs) within the tumor." (PMID 39325360, 2025).
tumor (continued). "CTLA4, a crucial immune checkpoint receptor, plays a significant role in T-cell regulation and immune suppression, enabling tumor survival." (PMID 40005446, 2025). "We injected CT26, 4T1 and B16F10 MMRd or MMRp cell lines in mice and used anti-TIM3/TIGIT/LAG3/CTLA4 alone or in combination with anti-PD-1, 14 days following tumor inoculation." (PMID 40027748, 2025). "Originally, a simple blockade of CTLA-4 was proposed, with the notion of ‘releasing the brakes’ by boosting the anti-tumour T-cell response." (PMID 40265076, 2025). "Recently, immune checkpoint inhibitors, particularly those targeting CTLA-4 and PD-1/PD-L1 pathways, have shown remarkable anti-tumor effects across various cancer types, marking a transformative era in cancer treatment." (PMID 40268893, 2025). "Immune checkpoint molecules—including PD-1, PD-L1, and CTLA-4—are pivotal to tumor immune evasion mechanisms, and monoclonal antibodies targeting these pathways have revolutionized cancer therapy." (PMID 40557143, 2025). "The increased expression of CTLA-4 and PD-1 is likely due to prolonged antigen stimulation, oncogenic signaling, and inflammation within the tumor microenvironment." (PMID 39325360, 2025). "This review examines the current literature and clinical trials on ICIs and CAR-T cell therapies in GBM, focusing on its unique characteristics of the tumor microenvironment and detailing the PD-1/PD-L1, CTLA-4, and CAR-T pathways." (PMID 39941829, 2025). "t-SNE visualization indicated a significantly higher distribution density of FOXP3, IL10, TGF-β1, and CTLA4 positive cells in the tumor group compared to the normal group, with gene expression concentrated in immune subpopulations like T cells." (PMID 41438510, 2025). "Although ICIs, such as CTLA-4 and PD-1/PD-L1 inhibitors, have demonstrated clinical efficacy, their therapeutic impact remains suboptimal due to patient-specific variability and tumor immune resistance." (PMID 40012016, 2025). "Immune checkpoint molecules, including PD-1/PD-L1 and CTLA-4 play a central role in tumor immune evasion." (PMID 41230456, 2025). "Single cell RNAseq analysis of tumor infiltrating CD8 T cells shows positive correlation of CTLA-4, TIM-3, LAG-3, TIGIT, GITR, 4-1BB, and OX40 with PD-1 but negative correlation of KLRG1 with PD-1." (PMID 39832302, 2025). "Previous studies consistently reported that the expressions of LAG-3, PD-1, PD-L1, CD28, CD80, CD27 and CTLA-4 were relevant to the immunosuppression in the tumor microenvironment." (PMID 39781354, 2025). "Recent research demonstrates that dual silencing of VISTA and CTLA‐4 markedly enhances anti‐tumor immune responses, improves the inflammatory cytokine milieu, and inhibits tumor progression, offering a novel approach to address TME heterogeneity." (PMID 40356222, 2025). "Specifically, they target key immune checkpoints such as PD-1/PD-L1 and CTLA-4, thereby activating T cells and promoting their recognition and destruction of tumor cells." (PMID 40308503, 2025). "In our study, a higher expression of the ICP molecule CD276 was shown in the tumor tissue, particularly in WLWH - IS, which was associated with increased expression of T cell exhaustion markers CTLA4 and LAG3 in different T cell subpopulations." (PMID 40393975, 2025). "ICOS agonists have shown potential in enhancing anti-tumor immunity, particularly in combination with CTLA-4 inhibitors." (PMID 39857682, 2025). "ICIs primarily counteract the immunosuppressive effects of tumor cells on T cells by blocking the interaction between immunosuppressive regulatory proteins on the cell surface, such as CTLA-4, PD-1, and PD-L1." (PMID 40012016, 2025). "In this context, we propose to investigate the efficacy of anti-CTLA-4 mAbs combined with anti-CD80 mAbs using a murine tumour model." (PMID 40725864, 2025).
tumor (continued). "Building on this, another study showed that VSV-NDV synergizes with immune checkpoint blockade (anti-CTLA-4), enhancing tumor-specific T cell activation via tumor RIG-I signaling, which was critical for the combined therapeutic effect." (PMID 41294689, 2025). "Immunotherapy specifically activates the anti-tumor activity of T lymphocytes by blocking the interactions between PD-1, PD-L1, and CTLA-4, thereby enabling T cells to specifically recognize and eliminate tumor cells while sparing normal tissues." (PMID 40018048, 2025). "Anti-PD-1 predominantly leads to the proliferation of exhausted-like CD8+ T cells within the tumor, whereas CTLA-4 inhibitor mainly results in the amplification of CD4+ effector cells and exhausted-like CD8+ T cells." (PMID 40861801, 2025). "Tumor-infiltrating CTLA-4+ Tregs evade anti-tumor immune responses by dampening effector T cell activities." (PMID 40607438, 2025). "The concurrent use of PD-1/PD-L1 inhibitors (e.g., nivolumab, pembrolizumab) and CTLA-4 inhibitors (e.g., ipilimumab) has demonstrated promising clinical outcomes across various tumor types." (PMID 40918452, 2025). "A subcutaneous xenograft nude mouse model was established to investigate the inhibitory effects of the combination regimen of CIK cells, chemotherapy, and cadonilimab (a PD-1/CTLA-4 bispecific antibody) on tumor growth and metastasis in vivo." (PMID 40539041, 2025). "Tumor growth was better controlled when CAN-2409 treatment was combined with anti–CTLA-4 antibody therapy compared with CAN-2409 + prodrug treatment alone." (PMID 39881590, 2025). "The virus facilitated the delivery and release of IL‐12 and CTLA‐4 directly into the tumor, significantly enhancing the anti‐tumor immune response." (PMID 39927632, 2025). "CTLA-4, highly expressed on Tregs, functions as an immunosuppressive molecule that facilitates tumor cell survival." (PMID 40607438, 2025). "The remodeling of tumor blood vessels and anti-angiogenic effects of anti-CTLA-4 antibodies require the presence of CD4+ T cells and the activity of IFNγ, a potent anti-angiogenic cytokine." (PMID 40460830, 2025). "In response to this induced antitumor immunity, tumors evade the host immune response by expressing immune-exhausting molecules, such as PD-1, PD-L1, and CTLA-4, on the surface of tumor cells or tumor-infiltrating cells in the TIME, and they grow and develop." (PMID 40647383, 2025). "Therapeutically, anti-CTLA-4 monoclonal antibodies, such as ipilimumab and tremelimumab, enhance anti-tumor immunity by blocking inhibitory CTLA-4 signals, and thereby restore T-cell effector function and increase CD28-mediated costimulation." (PMID 40723175, 2025). "These strategies include co-administration of PD-1/PD-L1 inhibitors with CTLA-4 antagonists or integration with MDSC-depleting agents or tumor vaccines to overcome resistance and enhance antitumor immunity." (PMID 40563466, 2025). "Immune checkpoint molecules, such as PD-1/PD-L1 and CTLA-4, are critical mediators of tumor immune escape, enabling tumor cells to evade immune surveillance by binding to receptors on T cells and suppressing their activity." (PMID 40303413, 2025). "ICIs, including anti‐PD‐1/PD‐L1 antibody and anti‐CTLA4 antibody, prevent exhaustion of CTLs and block immune evasion of tumor cells." (PMID 40257446, 2025). "In our study, CD8+ T cells across all groups exhibited modest expression levels of PD1 and CTLA-4, representing highly activated T cells, including tumor-reactive population." (PMID 41280919, 2025). "These advances highlight the potential of CTLA-4 blockade as a key strategy to overcome tumor-induced immunosuppression and enhance immunotherapy efficacy across several cancer types." (PMID 41394821, 2025).